HRAS (HRas proto-oncogene, GTPase)
Diseases named in the same sentence as HRAS in open-access papers (continued):
Sharing a sentence is not in itself a finding about the gene and the disease.
cancer (continued). "It was found that BRAF V600E, RET/PTC1 and TERT mutations were associated with aggressive characteristics, whereas BRAF K601E, HRAS, NRAS, KRAS, PAX8-PPARy mutations and tumors with no mutations are significantly less likely to be associated with high risk cancers." (PMID 33910629, 2021). "Interestingly, MCOLN1 knockdown or TRPML1 inhibition did not affect ERK phosphorylation and cell proliferation in cancer cells expressing wild-type HRAS, or in cells in which oncogenic HRAS was stably knocked down." (PMID 31526156, 2019). "This dual role in cancer and development is not unique to SETBP1; a growing number of genes in which germline mutations cause developmental disorders, such as HRAS, ASXL1, EZH2 and FGFR2, are also known to harbor overlapping somatic mutations which drive the development of cancer." (PMID 28346496, 2017). "For example, in our study HRAS (P = 5.0 × 10-46), AKT1 (P = 9.5 × 10-26), PIK3CA (P = 5.5 × 10-5), B2M (P = 6.7 × 10-4), and KDM5C (P = 3.5 × 10-3) were predicted to be putative cancer genes using Fisher’s exact test and evidently designated as cancer driver genes according to the 20/20 rule." (PMID 25360158, 2014). "As a non-exhaustive example, the iM in the HRAS oncogene was included in the list of candidates: it is known to form a double-hairpin structure and to play a crucial role in regulating HRAS gene expression, a key player in cell proliferation pathways and cancer progression." (PMID 40873684, 2025). "Moreover, the involvement of HRAS in cancer is not restricted to the RAS-MAPK pathway alone, as it extensively interacts with other pivotal signaling pathways and cellular processes, including but not limited to the PI3K-AKT pathway, Wnt signaling pathway and cytoskeleton." (PMID 37153521, 2023). "Meanwhile, HPV-positive and -negative tonsil cancers may likely have different preferences for cancer-related pathways and detailed somatic mutations: HPV-positive tumors tend to have higher rates of RB1, HRAS, and FGFR3 mutations." (PMID 36979829, 2023). "In addition, results from our research showed that HRAS genes were significantly enriched in the following KEGG signaling pathways: estrogen signaling pathway, serotonergic synapse, cholinergic synapse, chemokine signaling pathway, RAS signaling pathway, and pathways in cancer." (PMID 34580608, 2021). "This shows a previously unknown weakness of the HRAS proto-oncogene, namely that exon 2 is weakly defined and therefore is a suitable target for SSO-based therapy, thereby pointing towards a potential new direction for therapeutic targeting of RAS in anti-cancer treatment." (PMID 27195699, 2016). "Seven other cancer-related genes (BRAF, NRAS, HRAS, ERK1, ERK2, PTEN, and PIK3CA) were found negative for mutations." (PMID 40364006, 2025). "Further, we found six genes—FOXL2, TNFAIP3, CHD1L, HRAS, KIT, CTCF—that occurred in 12 cases that are not on the top 20 list of any of the four common cancers used for comparison." (PMID 32570879, 2020). "However, reports regarding PFGFRA, HRAS, AKT1, FLT3, and NOTCH1 are lacking in the TCGA tonsil cancer data." (PMID 36979829, 2023). "Oncogenic HRAS protein (rather than gene)-induced macropinocytosis was reported as early as 1986 by Bar-Sagi and Feramisco, when RAS oncogenes were considered to be one of the contributing events of certain types of human cancers." (PMID 35154489, 2022). "In contrast, reduction of PIP5K1A in the HRAS-mutant and NRAS-mutant human cancer cell lines typically either had no consistent effect or even an increase in the number of viable cells, with the exception of TYKNU cells, in which all three PIP5K1A sgRNAs led to a decrease in cell number." (PMID 30194290, 2018).
tumor (500 papers, 1986 to 2026). "In contrast, BRAFi acts as a potent tumour promoter able to drive MAPK paradoxical activation from a single copy of HRAS-mutated skin." (PMID 41507151, 2026). "Treatment of HRAS-mutant tumours with tipifarnib over long periods resulted in resistant tumours that harbour a mutation in NF1 and GNAS." (PMID 40332222, 2025). "For example, driver mutations of RAS genes (KRAS type, NRAS, and HRAS) lead to infinite proliferation and enhanced survival of tumor cells." (PMID 40778223, 2025). "Erastin, a ferroptosis inducer first discovered in 2003, was found to exhibit considerable lethality in human tumour cells harbouring mutations in the HRAS, KRA, and BRAF oncogenes." (PMID 40136465, 2025). "The genomic landscape of Spitz neoplasms includes fusions in genes such as ALK, ROS1, MET, RET, or BRAF and mutations in HRAS genes, which influence both the tumor’s biological behavior and morphological features." (PMID 40870546, 2025). "Intriguingly, we observed an apparent increase in tumor mutational burden across the FGFR3/HRAS, FGFR3 & chr9Del, GI, and AA-like subtypes." (PMID 40247187, 2025). "Due to their frequent spitzoid histomorphology, these neoplasms were initially proposed as a subset of Spitz tumours, alongside those driven by kinase gene fusions and HRAS mutations." (PMID 40107205, 2025). "One patient with advanced parotid adenocystic carcinoma, whose tumour had a mutation in HRAS remained on treatment with stable disease for 15 cycles; this is interesting in the context that HRAS has been proposed as a target for MEK1/2 inhibitors." (PMID 40211189, 2025). "Targeted therapies for patients with HRAS mutations, such as tipifarnib, currently exist and are being tested in various tumor types." (PMID 38672653, 2024). "RMC-7977, a compound that exhibits potent inhibition of the active states of mutant and wild-type KRAS, NRAS and HRAS variants has a strong anti-tumour effect on RAS-addicted tumours and is well tolerated in preclinical models." (PMID 38589574, 2024). "BRAF, NRAS, TG, TTN, and HRAS were the most frequently mutated genes in the early and late stages of the tumor; however, other genes were found to be more frequently mutated in the late stage." (PMID 37854594, 2023). "Inclusion of HRAS exon 5 is found to negatively correlate with MYC hallmark enrichment in the majority of 27 tumor types." (PMID 37399401, 2023). "We found that 2 miRNAs by targeting 2 metastasis-related mRNAs were correlated with tumor-infiltrating macrophages, HRAS, and BRAF gene mutation status." (PMID 38036953, 2023). "HRAS mutations affect farnesylation, and tumours with HRAS mutations are particularly susceptible to treatment with farnesyl-transferase inhibitors." (PMID 35739348, 2022). "In conclusion, if the HRAS mutation is present from fertilization onwards, tumor incidence depends on the specific mutation." (PMID 35266292, 2022). "HRAS deletions were associated with aggressive tumor features and poor survival, while HRAS expression has been linked with better prognosis." (PMID 36358725, 2022). "Among HRAS mutated tumours, single-base substitutions mutations occurring most frequently on codon 12 (27–33%), 13 (25–27%), or 61 (37–40%)." (PMID 35621690, 2022). "Several other mosaic HRAS variants with G12S mutations identified in various tumor types were also described, including cases of urothelial cell cancer and bladder cancer." (PMID 35266292, 2022). "Recent advances in genomic and cellular studies have led to the identification of HRAS mutations as drivers of tumor growth in a subset of HNSCC." (PMID 34771475, 2021).
tumor (continued). "Along these lines, it is interesting to note that DMBA, the tumor-initiating chemical carcinogen used in this study, is thought to act as a tumor initiator by inducing activating mutations in HRAS." (PMID 33435392, 2021). "Other surveys of both KRAS-mutated and HRAS-mutated patient tumor samples have found similar results." (PMID 33924994, 2021). "Such shifts are significant in posterior distributions of mutations, such as the S33P mutation in the CTNNB1 gene in the LIHC tumor type and the Q61R mutation in the HRAS gene in the THCA tumor type." (PMID 34424899, 2021). "KRAS appears to be mutated in 22% of the overall tumour population, while the frequency of HRAS mutation is 2% and NRAS mutation is 8% according to cumulative data." (PMID 32772213, 2020). "In a phase I trial, the MEK inhibitor RO5126766 induced 20% tumor shrinkage in patient with an HRAS mutation." (PMID 29641535, 2018). "For this study, we also screened the whole cohort for hotspot mutations of HRAS and found 10 of 202 (4.95%) mutated cases, corresponding exclusively to sporadic tumours." (PMID 25625332, 2015). "By comparison, Erastin has been reported to exhibit greater lethality in human tumor cells harboring mutations in the oncogenes HRAS, KRAS, or BRAF as well as in an individual genetic context using isogenic cell lines with and without oncogenic RAS genes." (PMID 26157704, 2015). "Knockout mice and wild-type mice were treated with two chemicals: DMBA, which causes mutations in a gene called HRas, and TPA, which promotes the formation of tumours from cells that contain HRas mutations." (PMID 24843010, 2014). "All the tumours identified with FGFR3 or HRAS mutations expressed SSX2-4 (7/7), whereas all OCT2-positive tumours were mutation-negative (4/4); however, these differences were not statistically significant." (PMID 21706474, 2011). "In addition, two variants of uncertain biologic significance were discovered in KIT (missense, p.K492R) and HRAS (nonsense, p.Q70*) as passenger mutations in a tumour (case 22M) with a concomitant NRAS mutation." (PMID 36416305, 2023). "OR analyses show a significant association between HRAS mutations and a high tumor stage (OR=3.63)." (PMID 35600380, 2022). "Systemic targeted treatments were delivered in three HER-negative cases, one within a clinical trial (olaparib followed by palbociclib), two owed to the evidence of actionable tumor mutations (1 tipifarnib for HRAS mutation, 1 dabrafenib and trametinib for BRAF mutation)." (PMID 36733354, 2022). "We hypothesized that when tested in RMS cell lines, xenografts or PDX that harbor activating mutations in HRAS, FTase inhibition will elicit genotype-dependent anti-tumor activity." (PMID 35459782, 2022). "HRAS mutations are closely associated with the occurrence of various tumours." (PMID 33479376, 2021). "Interestingly, the selection pressure on CASP8 in the context of TMD was seen across the entire tumor progression spectrum, while HRAS mutations appeared positively selected specifically in late-stage tumors." (PMID 34307377, 2021). "In tumor tissue overexpression of HRAS gene was associated with adenocarcinoma subtype (p = 0.049)." (PMID 33549031, 2021). "KRAS and HRAS mutations were detected in 35% (18/51) and 33% (17/51) of tumours, respectively." (PMID 31960612, 2020).
tumor (continued). "Normal or mutated forms of HRAS are overexpressed in multiple tumours 60-65." (PMID 31534544, 2019). "However, one tumor harbored a disease-associated variant in HRAS, and a BRAF p.(V600E) disease-associated variant was detected in another." (PMID 31046843, 2019). "We further performed Gene Set Enrichment Analysis (GSEA) and found that the differentially expressed genes between I P and I NP tumors were significantly overrepresented in signatures associated with ‘Hypoxia’, ‘EGF signaling’, ‘HRAS oncogenic’ and ‘Tumor angiogenesis’." (PMID 31039818, 2019). "In addition, somatic mutations in the previously known genes VHL, RET, MAX, and HRAS were found in one tumor each, in agreement with frequencies in previous reports." (PMID 29159601, 2018). "HRAS mutation was associated with the anti-tumor activity of QLNC120." (PMID 27902470, 2017). "Recently activating mutations in HIF2A and HRAS were reported in a subset of these tumours." (PMID 25883647, 2015). "Interestingly, any tumor but one with PIK3CA mutation additionally carried simultaneous HRAS mutations pointing to the parallel activation of the two major receptor tyrosine kinase downstream signaling pathways, a finding not reflected in previous studies." (PMID 26053092, 2015). "Yet our data indicates that, though rare, patients with HRAS mutated tumors of different tumor histology might benefit from targeted therapy." (PMID 26544513, 2015). "Interestingly, one phase I trial for the novel Mitogen-activated protein kinase kinase (MEK) inhibitor RO5126766 reported a tumor patient with HRAS mutation that showed 20% tumor shrinkage due to MEK inhibitor treatment." (PMID 26544513, 2015). "CNV and MLPA analyses performed on the tumor tissue, however, indicated the occurrence of additional entire chromosome 11 gain(s), which had not previously been observed, further indicating a role of a dosage effect for the mutated HRAS allele in tumorigenesis." (PMID 37636262, 2023). "Second, HRAS mutations are one of the major driver alterations in MIUBCs (5.1–20%), and there is a consistency in the type of HRAS mutations among different tumor samples obtained from the same patients with MIUBC, suggesting that the majority of recurrences in MIUBC are clonally related." (PMID 32460812, 2020). "Similarly, MEK inhibitor might be partly responsible for HRAS-mutated tumor reduction according to a phase I trial." (PMID 32984002, 2020). "Interestingly, the tumor formation promoted by the loss of SIRT6 is oncogene HRAS-independent." (PMID 28406396, 2017). "In terms of cell signaling and gene regulation, aberrant activation of signaling pathways (notably FGFR3 mutations or fusions, HRAS overexpression, and alterations in MAPK components such as MAP4K3) further promotes tumor growth and progression." (PMID 41590518, 2026). "Preclinical studies demonstrated that tipifarnib disrupts HRAS membrane localization and signaling, leading to tumor regression in HRAS-mutant HNSCC models, with efficacy tightly dependent on HRAS mutation status." (PMID 41375018, 2025). "In preclinical studies, it effectively reduced ERK phosphorylation and inhibited KRAS-mutant tumor growth while sparing HRAS and NRAS." (PMID 41373672, 2025). "On the other hand, we report the somatic mutational landscape of HCC in our cohort, identified exclusively in the tumor tissues, with APC (100%), ALK (94%), HNF1A (56%), CDKN2A and HRAS (50%) emerging as the most frequently mutated genes." (PMID 41567639, 2025). "We also used Sanger sequencing to detect six genes—KRAS, NRAS, HRAS, TERT, RET, and BRAF—in the tumor tissue and identified a C228T mutation in the TERT promoter region." (PMID 41488090, 2025). "BRAF p.Val600Glu mutations were found in three left‐sided and 1 right‐sided tumour, NRAS p.Gln61Lys in 1 right and 1 left‐sided tumour, KRAS p.Lys147Glu and p.Ala146Thr in one left‐sided tumour, and HRAS p.Ala121Thr in the tumour of the rectum." (PMID 40302146, 2025).
tumor (continued). "Studies documenting relapse rates reported correlations between lower disease-free survival and increased Cyclin D1 or VEGF expression, and between increased tumor recurrence and decreased Cornulin expression or increased HRAS expression." (PMID 41465166, 2025). "The strategy followed for KRAS.SOS1 ternary complex can be extended to other RAS proteins involved in tumor progression, such as targeting the HRAS.SOS1 ternary complex with known 3-dimensional structure." (PMID 40244134, 2025). "The sequencing of the F1 (MSO) and F2 (PTC) probands’ tumours unveiled somatic BRAF and HRAS variants, respectively." (PMID 38396644, 2024). "Particularly the implication of the HRAS-ERK pathway is very well understood in cutaneous SCC, where HRAS oncogene is frequently mutated and used as a tumor driver in mouse models." (PMID 38951654, 2024). "Mutation of KRAS, neuroblastoma RAS viral (v-ras) oncogene homolog (NRAS), and Harvey rat sarcoma viral oncogene homolog (HRAS) are located in codon 12, with a frequency of 20 to 100% in tumor progression." (PMID 39057671, 2024). "Specifically, HRAS mutation was the most significant mutation type related to IC50 of BPTES, and cetuximab and vinorelbine were the two anti-tumor drugs related to GLS most closely." (PMID 38566121, 2024). "HRAS activation has been reported in several tumor types and can lead to the activation of signaling pathways, which play a role in cell growth and division." (PMID 39459475, 2024). "HRAS expression was significantly higher in HRASmt compared to HRASwt tumors (transcripts per parts million [TPM]) among all investigated tumor types." (PMID 38672653, 2024). "Additional analyses showed that HRAS exon 5 PSI is positively correlated with HNRNPH1 gene expression across tumor types and negatively correlated with HNRNPF expression." (PMID 37399401, 2023). "The HRAS gene and its protein product have significant roles in tumour genesis by regulating fundamental cellular processes such as growth, differentiation, and viability." (PMID 37153521, 2023). "Variants in 5 genes (RPN1, CDKN2A, HRAS, PALB2, CBFA2T3) have been identified in 32 individuals with tumor from the extended cohort and classified as pathogenic, likely pathogenic, and VUS." (PMID 36845707, 2023). "In each of the HRAS-mutant models, tumors regrowth occurred after cessation of exposure to tipifarnib, with mild tumor regression on retreatment." (PMID 35459782, 2022). "We observed that the overexpression of HRAS in the tumor tissues compared to matched healthy tissues significantly correlated with responsiveness of primary NET cells to lenvatinib (p=.048)." (PMID 36743926, 2022). "Due to the development of RAS mutations profiling, tipifarnib appeared as an interesting strategy to inhibit HRAS-mutant tumours." (PMID 35621690, 2022). "Tipifarnib, a farnesyl transferase inhibitor, is a promising candidate to target HRAS-mutant tumours and should be explored in NSCLC patients." (PMID 35621690, 2022). "HRAS and JAK1 mutations are less frequent in tumours with high NCS and KRAS mutations are under-represented in samples with high SCS." (PMID 35326573, 2022).